SOX10 (SRY-box transcription factor 10)
Diseases named in the same sentence as SOX10 in open-access papers (continued):
Sharing a sentence is not in itself a finding about the gene and the disease.
cancer (96 papers, 2013 to 2026). A tumor composed of atypical neoplastic, often pleomorphic cells that invade other tissues. "SOX10 (SRY-related HMG-box 10) is a nuclear transcription factor that is commonly used to identify cancers of neural origin, but it has recently been linked to TNBC." (PMID 36120242, 2022). "It has been reported that SOX10 significantly regulates the proliferation, migration, and apoptosis of tumors and is closely associated with the progression of cancer." (PMID 33344444, 2020). "Ectopic expression of SOX10in SOX10-deficient cancer cells inhibits their proliferation, tumorigenicity, and metastatic potentials in vitro and in vivo." (PMID 25301735, 2014). "SOX10 is not only useful for confirming breast origin of tumors at metastatic sites but it is also performed on the breast samples as part of the diagnostic workup for poorly differentiated malignant neoplasm." (PMID 38813332, 2024). "However, the impact of SOX10 variants extends beyond developmental disorders, contributing to the initiation and progression of different cancers due to its involvement in numerous tissues." (PMID 38132479, 2023). "The biopsy of the nodular lesion revealed an undifferentiated malignant tumor, and immunohistochemical analysis using anti-SOX10, anti-Melan A, and anti-HMB45 antibodies confirmed melanocytic origin." (PMID 41982568, 2026). "To demonstrate that the RNA-binding activity of HK2 sustains its ability to regulate mRNA translation, we focused our study on one given mRNA (SOX10) that is also highly relevant in cancer." (PMID 40956859, 2025). "We demonstrate that the HK2 glucose kinase is a bona-fide RBP that regulates the translation of the SOX10 mRNA, thereby regulating cancer-relevant phenotypes." (PMID 40956859, 2025). "Analysis of SOX10 expression in pan-cancer tissues by GEPIA revealed that SOX10 was significantly highly expressed in SKCM." (PMID 40342816, 2025). "Promoters’ analysis highlighted enriched transcription factor binding sites for developmental genes, such as HOX and SOX family genes (HOXB13 and SOX10), and for well-known cancer-related genes, like BRCA1." (PMID 38891761, 2024). "In previous studies associated with cancer progression, UBE2N mostly functioned on the activation/inactivation of cancer-related signaling pathways (e.g., MEK/FRA1/SOX10 and TAK1-p38 MAP kinase cascade)." (PMID 38715121, 2024). "SOX8, SOX9, and SOX10 play diverse roles in different cancers, influencing processes such as differentiation, proliferation, invasion, and tumorigenesis." (PMID 38132479, 2023). "Sex determining region Y-BOX 10 (SOX10) is a transcription factor, which involved in the occurrence and development of various cancers." (PMID 35585935, 2022). "We explored correlations between SOX10 and enrichment scores of metabolism-pertinent pathways and cancer-immune cascade steps by GSVA." (PMID 36524115, 2022). "Then, to thoroughly analyze the prospective merit of SOX10 as a new immune target in pan-cancer, sensitive drugs predicated on SOX10 expression were predicted." (PMID 36524115, 2022). "Meanwhile, SLC25A13 and its neighboring genes were enriched in transcription factor target genes, including MEF2C, NCOA2, SNAI1, and SOX10 target genes, which were participated in the cancer progression." (PMID 35607442, 2022). "To this end, we screened a total of 1820 compounds using the anti-cancer library compound panel in parental and SOX10 knockout MeWo cells." (PMID 35296667, 2022).
cancer (continued). "Perhaps there is a relationship between the downregulation of miR-19a-3p and SOX10 (SRY-box transcription factor 10) suppression, both causing TGF-β signaling activation in different types of cancers." (PMID 34769348, 2021). "In contrast, the cancer stem cell marker molecule SOX10 was rather uniformly expressed in all eight cells." (PMID 31892524, 2020). "Initially, we introduce the basic background of the SOX family and SOX10 and discuss the pathophysiological roles of SOX10 in cancer." (PMID 33344444, 2020). "In this review, we first introduce the basic background of the SOX family and SOX10 and then discuss the pathophysiological roles of SOX10 in cancer." (PMID 33344444, 2020). "Then, we enumerate the application of SOX10 in pathological diagnosis and therapeutic potential in cancer." (PMID 33344444, 2020). "Recently, SOX10 has received more attention due to its involvement in the genesis and development of various cancers." (PMID 33344444, 2020). "This is surprising as especially SOX10 has prompted recent interest and has been reported in various other cancer entities." (PMID 30205833, 2018). "In fact, the SOX family, especially SOX10, identified in the present study, regulates cancer stem cell properties of TNBC cells and participate in early determination and migration." (PMID 30175120, 2018). "TRIM2 is a diagnostically significant and conserved element of the SOX10 signature in BBC (breast basal-like carcinomas) cell lines." (PMID 27911271, 2017). "Upregulation of SOX10 protein has been observed in multiple cancer types, including melanocytic tumors and tumors of the nervous system." (PMID 26461473, 2015). "Specifically expressed in myoepithelial cells and breast basal-like carcinomas, SOX9 and SOX10 have proven to be negatively associated with FOXA1, which encodes FoxA1 transcription factor, an essential regulator of mammary ductal morphogenesis." (PMID 25962646, 2015). "SOX10 expression in ACC appears to be a part of a highly coordinated transcriptional program characteristic of cancers with basal/myoepithelial features." (PMID 24828201, 2014). "Of the 13 recurrently underexpressed SOX genes, SOX3, SOX5, SOX7 and SOX10 were exclusively underexpressed (i.e. they showed overexpression frequencies <20% in all cancer types)." (PMID 25594027, 2014). "Together, these findings demonstrated the unexpected role of SOX10 as an important DNA binding transcription factor that recruits β-catenin to repress Wnt/β-catenin signaling in cancer progression." (PMID 25301735, 2014). "SOX10 was also found to be downregulated in multiple other carcinoma cell lines including nasopharyngeal, lung, and breast (data not shown)." (PMID 25301735, 2014). "Given this critical role, targeting SOX10 inhibition may represent a promising therapeutic strategy for cancer treatment." (PMID 40159622, 2025). "We investigated whether HK2 contributes to cancer-related phenotypes by modulating SOX10 mRNA translation." (PMID 40956859, 2025). "Furthermore, SOX10 can directly bind to the MITF promoter to activate its transcription, regulating genes associated with cancer hallmarks." (PMID 40458894, 2025). "This suggests SOX10 could be a key regulator of phenotypic transition across different cancer types." (PMID 39285246, 2024). "Furthermore, SOX9, SOX10, and SOX11 are associated with increased tumor metastasis and worse overall survival by regulating the ability of cancer cells to undergo EMT and acquire mesenchymal characteristics." (PMID 37444447, 2023). "However, the knockout of SOX10 in existing cancers can lead to acquired resistance against chemotherapeutic efforts." (PMID 38132479, 2023). "SOX10 also has pleiotropic effects in cancer-immune cascade steps." (PMID 36524115, 2022). "The information compiled herein may assist in additional studies and increase the potential of SOX10 as a therapeutic target for cancer." (PMID 33344444, 2020).
cancer (continued). "Therefore, we have carefully summarized the recent literature to review the roles of SOX10 in cancer." (PMID 33344444, 2020). "Collectively, the information compiled here comprehensively characterizes the roles of SOX10 in cancer, which may potentially provide a novel theoretical basis for the early clinical diagnosis, prognosis judgment, and treatment of cancer." (PMID 33344444, 2020). "Consequently, SOX10 can be used as a potential target for cancer treatment, which is helpful for oncologists and pathologists to seek new developments for the diagnosis and therapeutic strategies of tumors." (PMID 33344444, 2020). "Besides, we enumerate the application of SOX10 in the pathological diagnosis and therapeutic potential of cancer." (PMID 33344444, 2020). "In this review, we focus on the emerging roles of SOX10 in the development of various cancers." (PMID 33344444, 2020). "SRY-Box 10 (SOX10) induced nestin expression regulates cancer stem cell properties of TNBC cells." (PMID 30175120, 2018). "SOX10 was identified as a methylated gene in our previous cancer methylome study." (PMID 25301735, 2014). "Therefore, the expression and functional role of SOX10 in cancer development needs more detailed investigation." (PMID 25301735, 2014). "SOX10 mRNA was significantly induced in treated cancer cells." (PMID 25301735, 2014). "Similarly, we further explored whether SOX10 directly promotes GAPDHS expression and whether GAPDHS is critical for SOX10-regulated cancer proliferation in vivo." (PMID 34249897, 2021). "Additionally, SOX10 have been identified to play essential roles in cancer stem cell self-renewal." (PMID 33643898, 2020). "We found that while almost all cancer cells expressed OPC-associated signal transduction factors OLIG1, OLIG2, and PDGFRA, expression of progenitor-associated transcription factors such as SOX2 and SOX10 were highly expressed in cells expressing the MAPK programme." (PMID 31427603, 2019). "For example, both POU2F3 and SOX10 also bind RUVBL1/2 in an ATPase-dependent manner, and RUVBL1/2 inhibition broadly suppresses lineage-specific gene expression across several cancer types." (PMID 41241675, 2025). "The commonly used IHC markers to support a diagnosis of a carcinoma of breast primary include mammaglobin, gross cystic disease fluid protein 15 (GCDFP-15), GATA binding protein 3 (GATA3), and SRY-related HMG box 10 (SOX10), in addition to hormone receptors." (PMID 40025593, 2025). "The sensitivity and specificity of TRPS1 in determining carcinoma of breast origin were compared with those of GATA3 and SOX10." (PMID 40025593, 2025). "Our study demonstrated a higher sensitivity of TRPS1 in establishing carcinoma of breast origin compared with GATA3 and SOX10, consistent with previous reported studies." (PMID 40025593, 2025). "Our study demonstrated a higher sensitivity of TRPS1 expression in establishing carcinoma of breast origin compared with GATA3 and SOX10, consistent with previous reported studies." (PMID 40025593, 2025). "Excluding the spindle cell subtype, all metaplastic carcinomas in this cohort were positive for either pankeratin, GATA3 or SOX10." (PMID 37306115, 2024). "For the context-depend on partners of p-TEFb including NF-kB in many types of cancer cells, SOX2 and SOX10 in Schwann cells, Mediator both in serval cancer cells and pluripotent stem cells, and c-MYC in pluripotent stem cells." (PMID 36875763, 2023). "The magnitude of this facilitation was more prominent than SOX10, a top candidate identified to promote CTL-derived killing of cancer cells." (PMID 37835514, 2023). "The high expression of SOX10 is related to a shorter OS in LGG, HGG, and pan-cancer groups but benefited from the immunotherapy." (PMID 36524115, 2022). "SOX10 is a neural crest stem cell (NCSC) specifier and candidate mediator of phenotypic plasticity in cancer." (PMID 35501337, 2022).
cancer (continued). "Genes such as KIF5A, SOX10, MYL9, TRIM9, MYH11, and SNAP25 are known to play important roles in biological development, suggesting that LRP1B may also be a key factor in cancer." (PMID 40170839, 2025). "The immunophenotype in our case, positivity for HMB-45, Melan-A, and SOX10 with absence of pancytokeratin, confirmed melanocytic lineage while helping to exclude carcinoma." (PMID 40918809, 2025). "Carcinoma of apocrine differentiation consistently demonstrates an AR positive, SOX10 negative, K5 negative or focal immunophenotype." (PMID 37306115, 2024). "Carcinoma of apocrine differentiation demonstrated an AR positive, SOX10 negative, K5 negative/focal immunophenotype." (PMID 37306115, 2024). "Carcinoma of apocrine differentiation is characterized by an AR positive, SOX10 negative, K5 negative or focal immunophenotype." (PMID 37306115, 2024). "On the contrary, SOX9, SOX10, and SOX11 are upregulated in basal-like BC, indicating that therapeutic strategies targeting these factors may be beneficial for this subtype of cancer, which currently lacks targeted therapy." (PMID 37444447, 2023). "In contrast, SOX10 knockout MeWo cells failed to form palpable tumors, but luciferase imaging showed the presence of residual cancer cells at the sites of injection." (PMID 35296667, 2022). "SOX10, an essential transcriptional factor, belongs to the SOX family of transcription factors, which involved in the occurrence, development, and progression of multiple cancer types." (PMID 35585935, 2022). "MZF1, SOX10 and ZEB1 shRNAs displayed strong effect on survival of cancer cells." (PMID 28423538, 2017). "Furthermore, we aimed in the present study to evaluate the expression of nestin, NGFR, Sox10, FZD6 and PROM1 cancer stem cell markers and angiogenic factors in UM and to better understand the relationships between the detected markers and vasculogenic mimicry patterns." (PMID 33255843, 2020). "All MZF1 shRNAs, 4 out of 5 SOX10 shRNAs, and 2 of 3 ZEB1 shRNAs exhibited a strong effect on nearly all 212 cell lines, suggesting that these 3 TFs could be functionally essential in cancer cells." (PMID 28423538, 2017). "Interestingly, we analyzed the expression of a large panel of immunohistochemical markers and only SOX10 was more frequently expressed in ERBB2‐amplified ILBC, a marker that is typically positive in triple‐negative NST and non‐NST carcinomas." (PMID 38335502, 2024).
infection (8 papers, 2010 to 2024). The state of being infected such as from the introduction of a foreign agent such as serum, vaccine, antigenic substance or organism. "In both SOX10-deficient cells, a substantial reduction in VSVΔ51 infection and titers was observed, suggesting that SOX10 plays a key role in resistance to oncolytic virus therapy." (PMID 38201278, 2023). "Astrocytes were primarily productively infected, Sox10+ cells had a higher proportion of abortive infection, and microglia were mostly uninfected, with some exhibiting abortive infection." (PMID 39159381, 2024). "In contrast, the predominant infection state of Sox10+ cells was abortive infection (tdTomato+, GFP-), while Iba1+ cells were overwhelmingly tdTomato-/GFP-." (PMID 39159381, 2024). "In the present study, AAV with the best in vivo infection efficiency was selected for Sox10 delivery." (PMID 32363773, 2020). "However, when we disrupted IFN signaling, we observed only a slight shift toward more productive infection of Sox10+ cells and microglia." (PMID 39159381, 2024). "To assess whether infection had an effect on OL viability and glial activation, we performed immunostaining on brain slices from mice at day 8 p.i. using antibodies specific for OLs (SOX10+), mature OLs (SOX10+APC+), microglia (Iba1+) and astrocytes (GFAP+)." (PMID 37596606, 2023). "Finally, we find that both the induced resistant state and the loss of SOX10 induce the activation of ISGs independent of IFNα/β, priming the cells for resistance to infection by oncolytic viruses." (PMID 38201278, 2023). "Neither the number of mature (SOX10+APC+) nor immature (SOX10+APC−) OLs in the mPFC were affected by infection." (PMID 37596606, 2023). "On the contrary, neither Pparγ1 nor Pparγ2 was expressed in the SOX10+ cells generated by Sox10/c-Myc/Klf4 infection, showing that the SOX10+ cell population did not contain pre- or pro-adipocytes." (PMID 26873953, 2016). "Infection of the human melanocyte line Hermes 3A with shATF2 effectively inhibited ATF2 expression, upregulated Mitf transcription and increased transcription of SOX10 and FOXD3 (from 7- to 10-fold) and to a lesser extent of Pax3 and Brn2 (from 1.5- to 2-fold)." (PMID 21203491, 2010). "Likewise, immunoblots performed on blocks of tissue isolated from mPFC, cerebellum, and hippocampus tissue of PBS- and IAV-inoculated mice indicated that infection did not alter abundance of MAG, MOG, or SOX10." (PMID 37596606, 2023).
peripheral neuropathies (6 papers, 2014 to 2025). "It is essential for maintaining the identity and proper development of these cells, and mutations in SOX-10 can lead to various neurological disorders, including peripheral neuropathies." (PMID 41304765, 2025). "Furthermore, we provide useful datasets for the scientific community and expand the mutational screening space for disease-causing mutations—or modifiers of disease—in patients with peripheral neuropathy and other SOX10-related phenotypes." (PMID 27821050, 2016). "The identification of additional SOX10 response elements and target loci will provide important information on the process of myelination in the peripheral nerve as well as novel target sequences to scrutinize for mutations and modifiers of peripheral neuropathy." (PMID 27821050, 2016).
adenocarcinoma (5 papers, 2021 to 2025). A common cancer characterized by the presence of malignant glandular cells. "Renal cell-like adenocarcinoma of the nasal cavity and paranasal sinuses is composed of cytoplasmic clear cuboidal cells which diffusely express S100 and SOX10." (PMID 40738062, 2025). "A specific subset of low-grade NITAC has been designated as sinonasal seromucinous adenocarcinomas due to consistent expression of seromucinous differentiation markers, including DOG1, SOX10, and S-100." (PMID 39493022, 2024). "One adenocarcinoma of the parotid gland showed a solid pattern without mucous secretion, and IHC was positive for S100, SOX10, and DOG1 and negative for NR4A3." (PMID 34036223, 2021).
neurological disorders (5 papers, 2010 to 2025). "Specifically, we performed targeted genomic re-sequencing of a collection of patients with neurological disease, focusing our attention on predicted SOX10- and EGR2-binding sites within evolutionarily conserved non-coding regions of the MPZ gene." (PMID 21179557, 2010). "However, none of the neurological disorders common in patients with SOX10 pathogenic variants were reported in individuals with WS4 that we reviewed." (PMID 41516007, 2025).
epithelial neoplasm (2 papers, 2021 to 2023). A benign or malignant neoplasm that arises from and is composed of epithelial cells. "In summary, while further research is needed to fully understand the extent of SOX10 expression in various epithelial neoplasms, it remains a promising marker for the diagnosis and prognosis development of several carcinomas." (PMID 38132479, 2023). "When examining the impact of SOX10 on epithelial neoplasms, its influence is extensive and continues to unfold with further investigations." (PMID 38132479, 2023). "Epithelial neoplasms further underscore SOX10’s clinical relevance." (PMID 38132479, 2023).
brain disorder (1 paper, 2025). A disease affecting the brain or part of the brain. "Finally, two BAG-associated hub transcription factor genes, KLF3 and SOX10, were identified as regulators of pleiotropic risk genes for diverse brain disorders." (PMID 40795387, 2025).